IDO1 (indoleamine 2,3-dioxygenase 1)
Diseases named in the same sentence as IDO1 in open-access papers (continued):
Sharing a sentence is not in itself a finding about the gene and the disease.
squamous cell carcinoma (6 papers, 2020 to 2026). A carcinoma arising from squamous epithelial cells. "Moreover, recent studies have associated the role of IDO1 in developing immunotherapy resistance in squamous cell carcinomas, independently from the tumor site." (PMID 33922388, 2021). "Low Kyn/Trp significantly correlated with low IDO1 expression and never-smoker patients; while high Kyn/Trp was significantly associated with older (≥68 years) patients, advanced tumor stage, and squamous cell carcinoma (Sqcc), rather than the adenocarcinoma (Adc) histotype." (PMID 33922388, 2021). "In squamous cell carcinoma, CD80 (FC = 0.88, P = .014), CTLA4 (FC = 0.80, P < .01), and IDO1 (FC = 0.84, P = .020) expression was lower in HRD cohorts compared with HRP." (PMID 41533995, 2026).
vulvovaginal candidiasis (6 papers, 2013 to 2022). Infection of the vulva and vagina with a fungus of the genus CANDIDA. "IDO1 has been demonstrated that deficiency of this gene was associated with vulvovaginal candidiasis (VVC) and risk factors for recurrent VVC." (PMID 34120578, 2021). "In vaginal candidiasis, the selective deficiency of IDO1 significantly increased fungal loads and tissue damage mediated by inflammatory cells and here a similar result was observed." (PMID 28791025, 2017). "Interestingly, in a model of murine vulvovaginal candidiasis an increased expression of AhR was observed in the vagina of both naïve and infected IDO1-deficient mice, suggesting a further mechanism of mutual transcriptional regulation between IDO1, the source of l-kyn, and its sensor AhR." (PMID 25360135, 2014).
allergic rhinitis (5 papers, 2011 to 2021). Inflammation of the nasal mucous membranes caused by an IgE-mediated response to external allergens. "In children, IDO-1 enzyme activity was lower in patients with allergic rhinitis than asthmatic and in comparison to children with AD who exhibited the highest IDO-1 activity." (PMID 33339279, 2020).
brain cancer (5 papers, 2019 to 2025). A primary or metastatic malignant neoplasm affecting the brain. "A phase I trial, which combined IDO1 inhibitor indoximod either with temozolomide or with radiation in children with progressive malignant brain tumors, reported that this combination was well tolerated with good quality of life." (PMID 36032151, 2022). "Indoleamine 2,3 dioxygenase 1 (IDO1) is a tryptophan catabolism enzyme commonly found in malignant brain tumors, which is related to the downstream kynurenic acid metabolic pathway." (PMID 33511267, 2020).
Cerebral ischemia (5 papers, 2018 to 2021). Restriction of arterial blood supply to the brain associated with insufficient oxygenation to support the metabolic requirements of the tissue. "The IDO1 is one of the most important enzymes of kynurenine pathway, whose metabolites play important role in brain ischemia and VaD56." (PMID 31937840, 2020).
chronic hepatitis C (5 papers, 2013 to 2020). "Moreover, the activation of IDO1 is enhanced in patients with chronic hepatitis C." (PMID 28465467, 2017).
delirium (5 papers, 2022 to 2023). A disorder characterized by confusion; inattentiveness; disorientation; illusions; hallucinations; agitation; and in some instances autonomic nervous system overactivity. "The selective interference of microglial IDO-1 or neuronal NMDAR to validate the implication of the IDO-1/QUIN/NMDAR axis-dependent microglia-neuron interaction in the pathogenesis of postoperative delirium will be investigated to consolidate the findings of current study." (PMID 36160165, 2022).
dementia (5 papers, 2014 to 2023). Loss of intellectual abilities interfering with an individual's social and occupational functions. "This raises the possibility of IDO-1 being a broadly applicable therapeutic target for neuroinflammation-associated brain disorders, including AD and related dementias, as well as MDD." (PMID 37371332, 2023).
fetal growth restriction (5 papers, 2014 to 2024). A fetus that does not grow beyond the 10th percentile of conventionally accepted weight for gestational age. "The expression of TDO is reduced in placentas from patients showing fetal growth restriction, although it is increased in patients with pre-eclampsia possibly as a compensation for reduced IDO1 expression." (PMID 33363543, 2020). "So far, little is known regarding the role of IDO1 in the context of intrauterine growth restriction (IUGR, synonymous with fetal growth restriction)." (PMID 24904580, 2014).
ischemic stroke (5 papers, 2018 to 2023). A stroke disorder caused by obstruction of blood flow to the brain, due to thrombotic (local blood clot formation) or embolic (due to a blood clot or other material traveling from another site) event. "We present data demonstrating associations between ischemic stroke and variants of four genes (TPH1, IDO1, KYAT1 and AADAT) encoding enzymes of Trp metabolism." (PMID 34680558, 2021). "Furthermore, we also wished to learn whether changes are detectable in the expression of TPH1, TPH2, IDO1, KYAT1 and AADAT genes in peripheral blood samples (PBS) of ischemic stroke patients during the course of the disease." (PMID 34680558, 2021).
lung squamous cell carcinoma (5 papers, 2020 to 2023). "Our studies have shown a poor prognostic significance of high IDO1 expression in squamous cell carcinoma of the lung." (PMID 33466316, 2021). "Analysis of prognostic significance of studied markers revealed that low IDO1 expression in tumor cells indicates poor prognosis in squamous cell lung carcinoma (HR = 2.405, p = 0.0467), which corresponds to its immunosuppressor properties." (PMID 33466316, 2021). "Four previous studies have assessed expression of IDO1 and PD-L1 proteins together in lung squamous cell carcinomas and adenocarcinomas by IHC or immunofluorescence." (PMID 32555523, 2020). "IDO1 expression was also reported to correlate with PD-L1 expression, and co-expressed IDO1 and PD-L1 may be an important target for immunotherapy in lung squamous cell carcinoma." (PMID 36059952, 2022). "Furthermore, this finding seems partially to confirm data obtained from our recent study, which demonstrated that squamous cell lung cancers with a high TIL density presented a concomitant higher IDO1 immunohistochemical expression." (PMID 33922388, 2021).
medulloblastoma (5 papers, 2016 to 2021). A malignant, invasive embryonal neoplasm arising from the cerebellum. "Medulloblastoma, the most common brain tumour in children, has a low mutation burden, but was found to upregulate IDO1 expression." (PMID 29875199, 2018). "IDO1 expression in medulloblastoma cells causing Treg expansion by CCL2 mediator." (PMID 34095111, 2021). "This systematic review highlights the mechanisms of resistance of mTOR inhibitors in medulloblastoma and includes IDO1, T cells, Mnk2, and eIF4E, as they prolong malignant cell survival." (PMID 35008889, 2021). "Therefore, upregulation of IDO1 can be classified as an immune escape mechanism, indicating a role for the immune system in the control of medulloblastoma progression." (PMID 29875199, 2018).
metabolic syndrome (5 papers, 2019 to 2024). A cluster of metabolic risk factors for CARDIOVASCULAR DISEASES and TYPE 2 DIABETES MELLITUS. "A second study revealed that targeting the shift in tryptophan catabolism by suppressing host IDO1 activity also promotes metabolic health in preclinical models of metabolic syndrome." (PMID 36144238, 2022). "An increased activity of IDO1 and increased serum Kyn levels are seen in individuals with metabolic syndrome, and correlations between the Kyn-to-Trp ratio and obesity, metabolic syndrome, BMI, and blood triglycerides have been described." (PMID 31125257, 2019).
myelodysplastic syndrome (5 papers, 2021 to 2025). A clonal hematopoietic disorder characterized by dysplasia and ineffective hematopoiesis in one or more of the hematopoietic cell lines. "In contrast, the TET2, FLT3, RUNX1, BCOR and spliceosome mutations were more common in the IDO1-high group, which were commonly enriched in myelodysplastic syndrome (MDS)-transformed AML." (PMID 40234305, 2025). "It is mainly used in ovarian cancer, melanoma, myelodysplastic syndrome, and myelodysplastic syndromes with a high specificity inhibition of IDO1." (PMID 37509627, 2023). "In AML and myelodysplastic syndromes, IDO1 expression has been identified as an independent adverse prognostic factor, able to impair immune response by Treg induction." (PMID 35884612, 2022). "MSCs, including those isolated from myelodysplastic syndrome (MDS) and AML patients, up-regulate IDO1 following pro-inflammatory stimulation." (PMID 34771483, 2021).
pancreatic adenocarcinoma (5 papers, 2009 to 2023). "Intriguingly, HCC827 cells appear to have higher IDO1 mRNA and protein in spheroid culture than in the monolayer cultures, which was also reported in CFPAC-1 pancreatic adenocarcinoma cells." (PMID 37985999, 2023).
toxoplasmosis (5 papers, 2012 to 2023). A parasitic disease contracted by the ingestion or fetal transmission of toxoplasma gondii. "It is possible that type II GRA15-dependent IL-1β production, which suppresses the IFN-γ-induced IDO1-dependent immune response via iNOS, might be involved in the pathogenesis of human toxoplasmosis." (PMID 30301855, 2018). "However, there is only little known about the role of IDO1 in mice during acute toxoplasmosis." (PMID 31231617, 2019). "In addition, STAT1-independent artificial induction of IDO1 could evade the TgIST-dependent virulence mechanism and offer a novel therapeutic strategy for treating human toxoplasmosis." (PMID 30283439, 2018). "Besides, STING could protect the host from toxoplasmosis in another IDO1-dependent way." (PMID 36825026, 2023). "During toxoplasmosis, AKT phosphorylated STING forms a heterodimer with TICAM2 to promote IRF3-dependent transcription of indoleamine-pyrrole-2,3-dioxygenase-1 (IDO1), which is a critical kinase limiting parasite replication." (PMID 36825026, 2023).
urothelial carcinoma (5 papers, 2019 to 2024). A malignant neoplasm derived from the transitional epithelium of the urinary tract (urinary bladder, ureter, urethra, or renal pelvis). "Indoleamine 2,3-dioxygenase 1 (IDO1) levels correlate with poor outcomes in urothelial carcinoma (UC)." (PMID 39054485, 2024). "Indoleamine 2,3- dioxygenase 1 (IDO1) is an immunosuppressive enzyme that has been correlated with shorter disease-specific survival in patients with urothelial carcinoma (UC)." (PMID 39054491, 2024). "In two trials in uroepithelial carcinoma, the IDO1 inhibitor Epacadostat combined with pablizumab demonstrated a higher objective remission rate (ORR) compared to the pablizumab group, but no benefit was observed from combining Epacadostat in trials in other tumors." (PMID 39678512, 2024).
acute hepatitis B (4 papers, 2017 to 2025). "It was recently reported that IDO1 acts as an effector and an indicator of protective immune responses in patients with acute hepatitis B. The activation of IDO1 is vigorous in the early phase and is a hallmark of successful HBV clearance in patients with acute hepatitis." (PMID 28465467, 2017).
Chronic colitis (4 papers, 2013 to 2023). A chronic inflammatory disease of the large intestine (colon, cecum and rectum). "Enhanced IDO1 activity by NAS treatment protects the intestinal mucosa during the recovery phase of chronic colitis." (PMID 36798536, 2023). "However, in the following stages of chronic colitis IDO1 activity decreases along with the disease severity." (PMID 36798536, 2023). "In this study, we investigated IDO1 expression and activity in a mouse model of DSS-induced chronic colitis as well as in colon biopsies and sera from IBD patients." (PMID 36798536, 2023). "Chronic colitis was induced in mice through the oral administration of dextran sodium sulfate (DSS), and IDO1 activity was induced by i.p. treatment with N-acetyl serotonin (NAS)." (PMID 36798536, 2023). "Here, we investigated IDO1 expression and activity in a mouse model of DSS-induced chronic colitis as well as in colon biopsies and sera from IBD patients." (PMID 36798536, 2023). "In order to analyze IDO1 levels throughout the course of the DSS chronic colitis model, mice were euthanized at day 7, 14, 21, 28, 35, or 42 after first DSS administration, and IDO1 expression was analyzed." (PMID 36798536, 2023). "However, we noticed that the addition of fucose during chronic colitis normalized serum tryptophan, but affected neither Ido1 nor proinflammatory gene expression." (PMID 32053891, 2020). "Gal-3 is required for optimal toll-like receptor (TLR)-4-dependent activation of indoleamine 2,3-dioxygenase-1/kynurenine (IDO-1/KYN) pathway in DCs which promotes expansion of colon-infiltrated T regulatory cells (Tregs), and therefore, suppresses Th1 and Th17 cell-driven chronic colitis." (PMID 31336879, 2019).
co-infection (4 papers, 2022 to 2023). "Altered tryptophan metabolism via the kynurenine pathway as a result of increased indoleamine 2,3-dioxygenase 1 activity is a well-established consequence of various inflammatory conditions, including HIV, TB and HIV/TB co-infection." (PMID 37592227, 2023). "Three of the mechanisms that EBV uses to transform the TME are explored in this paper, including overexpression of IDO1, synergism between H. pylori and EBV co-infection, and M1 to M2 macrophage switch." (PMID 36421674, 2022). "We proceed to present three mechanisms: IDO1 overexpression, synergism between H. pylori and EBV during co-infection, and M1 to M2 pro-oncogenic transformation." (PMID 36421674, 2022).
colon adenocarcinoma (4 papers, 2021 to 2025). "Bioinformatic analysis demonstrates that indoleamine 2,3-dioxygenase 1 and 3-hydroxy-3-methylglutaryl coenzyme A reductase (key enzymes of kynurenine (Kyn) and cholesterol metabolism, respectively), are overexpressed in human colon adenocarcinoma tissues." (PMID 41432057, 2025).
encephalitis (4 papers, 2011 to 2021). An acute inflammatory process affecting the brain parenchyma. "However, recent research indicates that IDO1 deletion increases the incidence of seizures in acute TMEV-induced encephalitis." (PMID 33679331, 2021). "Thus, IDO1 is thought to be activated during seizures secondary to encephalitis." (PMID 33679331, 2021). "A recent study suggested that IDO1 deletion promotes seizures and neuropathogenesis in acute Theiler’s murine encephalitis virus (TMEV)-induced encephalitis." (PMID 33679331, 2021).
esophageal adenocarcinoma (4 papers, 2020 to 2025). A malignant tumor with glandular differentiation arising predominantly from Barrett mucosa in the lower third of the esophagus. "Moreover, patients with MDM2-amplified esophageal adenocarcinoma could be eligible for inhibitors of the tryptophan metabolism, like IDO1 enzyme inhibitors." (PMID 41299419, 2025). "IDO1 expression was seen in oesophageal adenocarcinoma but had no impact on survival." (PMID 37527282, 2023).
fibrosis (4 papers, 2017 to 2022). the formation of excess fibrous connective tissue in an organ or tissue in a reparative or reactive process. "The level of TRP in the IDO1–/– fibrosis mice was significantly lower than those in the WT fibrosis mice." (PMID 28465467, 2017). "Then, we discovered that the level of TRP in the IDO1–/– fibrosis mice was significantly lower than those in the WT fibrosis mice." (PMID 28465467, 2017). "We also discovered that TDO, another rate-limiting enzyme of TRP oxidation, and GCN2 was overexpressed in the liver tissues of the IDO1–/– fibrosis mice compared with the WT fibrosis mice or IDO1–/– control mice." (PMID 28465467, 2017). "The decreased proliferation of Th17 cells in IDO1–/– fibrosis mice is probably triggered by GCN2 kinase." (PMID 28465467, 2017). "The body weights of the WT model mice were lower than those of the IDO1–/– fibrosis mice at each time point." (PMID 28465467, 2017). "Consistent with the literature, we found that the expression levels of IL-6, TNF-α and TGF-β1, triggering the activation of HSCs, were decreased significantly in the liver tissues of the IDO1–/– fibrosis mice." (PMID 28465467, 2017). "In contrast, the IDO1–/– fibrosis mice had higher level of KYN in liver tissues than did the WT fibrosis mice." (PMID 28465467, 2017). "A terminal deoxynucleotidyl transferase dUTP nick-end labelling (TUNEL) assessment revealed that the IDO1–/– fibrosis mice had lower rates of apoptotic cell death in liver tissues than the WT fibrosis mice." (PMID 28465467, 2017). "Furthermore, the levels of serum ALT and AST in the IDO1–/– fibrosis mice were both significantly lower than those in the WT fibrosis mice, which indicated that hepatocytes were less damaged in the IDO1–/– model mice." (PMID 28465467, 2017). "Furthermore, IL-17a and the mRNA expression levels of IL-6, TNF-α and TGF-β1 were decreased in the liver tissues of the IDO1–/– fibrosis mice compared with the WT fibrosis mice." (PMID 28465467, 2017). "Furthermore, the expression of TDO and GCN2 kinase in liver tissues were increased in the IDO1–/– fibrosis mice compared with the WT fibrosis mice." (PMID 28465467, 2017). "Additionally, an IDO1 inhibitor (1-methyl-D-tryptophan) was administered to WT fibrosis mice." (PMID 28465467, 2017). "However, we found that Th17 cells were decreased in the IDO1–/– fibrosis mice." (PMID 28465467, 2017). "The reason for the positive correlations of the serum IDO1 level with liver lesions and fibrosis degree is not yet known." (PMID 28465467, 2017).
gastric tumor (4 papers, 2021 to 2023). "Stomach tumors with PTEN HemDel also had downregulation of Indoleamine 2,3-Dioxygenase 1 (IDO1) gene." (PMID 36977733, 2023). "Interestingly, IDO1 levels, but not IDO2 levels (not expressed), were significantly elevated in high AhR expressing gastric tumors." (PMID 35203450, 2022).
intestinal tumors (4 papers, 2020 to 2022). "In summary, we identified Stat1-dependent IDO1+ Paneth cells in intestinal tumors and normal intestinal crypts." (PMID 32444775, 2020). "Moreover, the number of IDO1+ Paneth cells was comparable in Ifnar1flox/floxApcMin and Ifnar1∆IECApcMin intestinal tumors." (PMID 32444775, 2020).
kidney cancer (4 papers, 2021 to 2025). Primary or metastatic malignant neoplasm involving the kidney. "The selective IDO1 inhibitor, epacadostat, when combined with pembrolizumab led encouraging results (partial response or stable disease) in 7 of 11 (63.6%) previously treated patients with kidney cancer." (PMID 33803184, 2021). "However, due to the strong preclinical rationale, other agents (potent IDO inhibitors such as linrodostat, and the long-acting IDO1 inhibitor KHK2455) are being developed for testing in patients with advanced kidney cancer." (PMID 33803184, 2021).
leiomyosarcoma (4 papers, 2018 to 2023). An uncommon, aggressive malignant smooth muscle neoplasm, usually occurring in post-menopausal women. "As expected, increased expression of IDO1, CTLA4, and PDL1 was observed in Oncopig leiomyosarcoma tumors relative to control muscle samples." (PMID 29930558, 2018).
metastatic carcinoma (4 papers, 2009 to 2024). A carcinoma which has spread from the original site of growth to another anatomic site. "Interestingly, we found a moderate correlation (r = 0.07) of IDO1 expression between the primary and metastatic cancer cells." (PMID 38736462, 2024). "Primary and metastatic cancer cells showed similar levels of IDO1 expression." (PMID 38736462, 2024).